NLRP3 (NLR family pyrin domain containing 3)
Diseases named in the same sentence as NLRP3 in open-access papers (continued):
Sharing a sentence is not in itself a finding about the gene and the disease.
tumor (continued). "Moreover, in vivo investigations suggested the activation of NLRP3 inflammasome and pyroptosis mechanisms as a consequence of PTX delivery by the GF-based scaffolds at the tumor sites." (PMID 39940603, 2025). "Serum levels of pyroptosis markers (NLRP3, HMGB1, and caspase‐1) and conventional tumor markers, including carcinoembryonic antigen (CEA), cancer antigen 125 (CA125), and cancer antigen 15‐3 (CA15‐3), were measured using enzyme‐linked immunosorbent assay (ELISA) kits." (PMID 41479846, 2025). "The expression changes of NLRP3 and S100A8 in various solid tumors varied widely, suggesting that NLRP3 and S100A8 had multiple regulatory functions in regulating inflammatory vesicle formation with tumor immune evolution and inflammatory pathways." (PMID 40535567, 2025). "In addition, the expression levels of NLRP3, caspase-1, IL-1β, and NF-κB were markedly elevated in CRC, particularly in high-grade tumours." (PMID 41148809, 2025). "Similarly, homogeneous Polyporus polysaccharide (HPP) repolarizes TAMs in bladder cancer via NF-κB/NLRP3 signaling, creating an anti-TME that indirectly induces autophagy in cancer cells by inhibiting the PI3K/Akt/mTOR pathway in macrophage–tumor cocultures." (PMID 41355895, 2025). "Additionally, under oxidative stress induced by the tumor microenvironment, thioredoxin-interacting protein (TXNIP) interacts with the NLRP3 inflammasome, leading to IL-1β maturation and secretion, which correlates with postoperative RCC recurrence." (PMID 40718836, 2025). "Despite these findings, the exact role of inflammation, and more precisely the NLRP3 inflammasome, in tumor progression has not yet been investigated." (PMID 39969214, 2025). "In AP, it promotes NLRP3 inflammasome-mediated pyroptosis and inflammation, whereas in PC, circERC1 inhibits pyroptosis—a pro-inflammatory cell death process—by disrupting the hnRNPA1-PKM2-NLRP3 axis, thereby promoting tumor cell survival and drug resistance." (PMID 41367614, 2025). "Mechanistically, NLRP3 was shown to interact directly with the TGF-β receptor, promoting mothers against decapentaplegic homolog 3 (SMAD3) phosphorylation and facilitating Th17-to-Treg trans-differentiation within the tumor microenvironment." (PMID 41291696, 2025). "Due to the vital link between the proliferative and migratory capacities of tumor cells and the epithelial-mesenchymal transition (EMT) process, our initial investigation evaluated the regulatory function of NLRP3 expression in the EMT progression of CRC cells." (PMID 39744485, 2025). "PCR results revealed a significant increase in the mRNA expression levels of caspase-1, caspase-11, NLRP3, and GSDMD in the transplanted tumor tissues when LINC00365 was downregulated, and western blot analysis revealed a significant increase in the expression of the corresponding proteins." (PMID 39439418, 2024). "Measurement of tumor volume after 30 days showed that compared to the control group, the subcutaneous tumor volume significantly decreased in the MLT group, si-NLRP3 group, and IL-1β Ab group, while it significantly increased in the oe-NLRP3 group and IL-18 Ab group." (PMID 39230586, 2024). "On the other hand, the inhibition of NLRP3 inflammasome using MCC950 reduced LPS, ATP, PTX-mediated caspase-1 and IL-1β release, both in normal cells (p < 0.01 and p < 0.001, respectively) and tumor cells (p < 0.001 and p < 0.0001, respectively)." (PMID 39433537, 2024). "After NLRP3-specific inhibitor MCC950 was added, the levels of NLRP3, ASC, NOD2 and AIM2 statistically decreased (p < 0.001 and p < 0.0001) upon stimulation with LPS and ATP of tumor cells." (PMID 39433537, 2024). "Therefore, the inhibition of the NLRP3 and implicitly the decrease of the pro-inflammatory markers can reduce the side effects of the PTX treatment, facilitating the anti-tumor therapy." (PMID 39433537, 2024). "Both NLRP3 and PLCG1 have been identified as such genes in a study of 379 OC tumour samples." (PMID 39516433, 2024).
tumor (continued). "We isolated the tumours and performed IHC analysis using ATG5, GPX4, NLRP3, and Ki-67 staining." (PMID 38499622, 2024). "Cell function experiments and nude mouse tumor transplantation assays confirmed that LINC00365 could regulate the expressions of pyroptosis-related proteins such as Caspase-1, Caspase-11, NLRP3 and GSDMD." (PMID 39439418, 2024). "Moreover, the potential of NLRP3 inhibitors such as MCC950 and colchicine in suppressing tumor growth has been demonstrated in experimental models of head and neck squamous cell carcinoma and gastric cancer." (PMID 39301197, 2024). "Experimental data indicated that NLRP3 is an important inhibitor of NK cell-mediated control of carcinogenesis and metastasis in the lung TME, manifested by increased activation of NK cells in tumor invasion and enhanced anti-metastasis response." (PMID 38553639, 2024). "More recent findings emphasize the key role of nucleotide‐binding domain, leucine‐rich containing family, pyrin domain‐containing‐3 (NLRP3)/IL‐1β signaling in inducing the expansion of PMN‐MDSCs and subsequent suppression of anti‐tumor immunity in cutaneous melanoma." (PMID 38775220, 2024). "In a murine model of HNSCC, a novel NLRP3 inhibitor known as MCC950 demonstrated the ability to delay tumor growth, decrease levels of MDSCs, Tregs, and TAMs, while also enhancing T cell infiltration within the tumor microenvironment (TME)." (PMID 39318624, 2024). "Additionally, a notable increase in tumor marker gene expression was observed in cells with functional NLRP1 and NLRP3 following UV radiation, whereas silencing these inflammasome genes altered the expression profiles of these markers." (PMID 39839625, 2024). "Nig could activate NLRP3 inflammasome and caspase‐1 protein to cleave GSDMD regulated by DAC, which could trigger murine 4T1 tumor cell pyroptosis for systemic anticancer immunity." (PMID 37125240, 2023). "In addition to secondary tumor shrinkage and reduced lung metastases, multiple pro-inflammatory cytokines were elevated in the serum of mice treated with XRT + NLRP3 or triple therapy, as assessed by multiplex ELISA." (PMID 37289257, 2023). "Moreover, to verify the protein expression of the four genes, including ENTPD1, NLRP3, TLR4, P2RX7, the HPA database was applied for inspection of the expression of the proteins deprived from them in LUAD tumor tissues and normal tissues." (PMID 37553698, 2023). "Interestingly, the NLRP3 inflammasome expression is negatively correlated to the number of effective CD4+ and CD8+ T cells that exert effects on anti-tumor immunity." (PMID 37705746, 2023). "A recent study just focused on NLRP3 inflammasome activation in the tumor parenchymal counterparts compared with non-cancerous counterparts." (PMID 38031068, 2023). "Regarding CNV analysis, we found that PANoptosis genes, especially NLRP3, RBCK1, PSTPIP2, and TNFAIP3, may promote tumor progression via CNV alteration." (PMID 36890219, 2023). "PD-1 blockade leads to CD8+ T cell activation and NLRP3 inflammasome activation, which results in the integration of granulocytic myeloid-derived suppressor cells (PMN-MDSCs) into tumors, and, ultimately, a tumor-permissive environment." (PMID 37242422, 2023). "While some studies show a tumor suppressive role of NLRP3, others demonstrate a pronounced negative impact." (PMID 37891577, 2023). "Since the NLRP3 inflammasome can be formed and activated by DAMPs, PLK2-induced DAMPs release could also be important for GSDMD pathway activation in USP18 depleted tumor environment in vivo." (PMID 36646704, 2023). "In a mouse study, lack of NLRP3 significantly reduced the tumor burdens of methylcholanthrene-induced sarcomas and from experimental and spontaneous metastasis in a natural killer cell– and IFN-γ-dependent manner." (PMID 36669831, 2023).
tumor (continued). "miR-223-3p, targeting the pyrin alanine-containing NOD-like receptor family 3 (NLRP3) in HCC cells, has been shown to play an important role in this tumor’s biology, and it may be useful to ascertain the prognosis of the liver damage related to HCV infection." (PMID 37623439, 2023). "NLRP3 inflammasome levels have been shown to be higher in ESCC tumor tissues than in noncancerous tissues and to correlate positively with the Ki-67 proliferation index." (PMID 37081882, 2023). "The colocalisation and accumulation of NLRP3 and FATP2 with CD33 in fatty grafts demonstrated that NLRP3 and FATP2 might modulate MDSCs in post-transplant tumour recurrence." (PMID 37916155, 2023). "All these reported data suggest that a united mechanism for activating of NLRP3 inflammasome and its contribution to cancer has not emerged yet, so further studies are needed to clarify its role in each kind of tumor." (PMID 36763290, 2023). "Notably, genetic interference of LGSN effectively suppressed tumor formation by inhibiting GCSC stemness maintenance and provoking gasdermin-D-mediated pyroptosis through vimentin degradation/NLRP3 signaling." (PMID 37612301, 2023). "That is, there was no significant change in the protein level of NLRP3 derived from tumor parenchyma cells." (PMID 38031068, 2023). "Our data indicated that NLRP3 inflammasome in MDSCs was activated by arachidonic acid through FATP2 during fatty graft injury, and it further induced the IL-17 production of CD4+ T cells, promoting the tumour recurrence post liver transplantation." (PMID 37916155, 2023). "The NLRP3 inflammasome mediates pyroptosis and a study of its in vivo impact on the tumor process may allow applications of PCD targeting in tumor therapy." (PMID 37081882, 2023). "NLRP3 inhibitor, MCC950, ameliorates anti-tumor immunity and dampens xenograft growth." (PMID 36932407, 2023). "NLRP3 protein expression was also shown to correlate with tumor node metastasis (TNM) and T stage but not with lymph node or metastasis status, gender or age." (PMID 37081882, 2023). "In contrast, LPS/ATP in MCF7 cells did not affect the tumor sphere size, where NLRP3 and IL-β were low." (PMID 36902278, 2023). "Indeed, IL-18 release is dependent on NLRP3 activation, and its signaling through the IL-18R receptor induces the exhaustion of CD8+ T cells and limited migration into the tumor." (PMID 37298187, 2023). "Similar to our previous findings, it appears that proliferation is independent of the NLRP3 activation capacity of tumor cells." (PMID 36902278, 2023). "However, compared with non-tumor samples, some PRGs with CNV gain, including NLRP3, were significantly downregulated in HCC (p < 0.01); some PRGs with CNV loss, including CASP3, were significantly upregulated in HCC (p < 0.001)." (PMID 36650832, 2023). "The proliferation of PDAC cells was closely related to the level of pro-inflammatory cytokines in the tumor microenvironment, rather than the level of NLRP3 expression in PDAC cells and macrophages." (PMID 38018872, 2023). "Consistent with the survival data, no enhanced tumor control was achieved for the 1Gy XRT set with or without NLRP3/α-PD1 as compared to XRT alone (all P > 0.05 vs. XRT)." (PMID 37289257, 2023). "Analyses of data from 1,097 breast primary tumors from the TCGA dataset confirmed that NLRP3 expression was lower in the primary tumor compared with normal tissues (132 normal breast tissues)." (PMID 36746533, 2023). "Moreover, IL-17A-mediated mitochondrial dysfunction induces ROS-induced activation of the NLRP3 inflammasome and cleavage of caspase-1, driving pyroptosis and eventually promoting CD8 + T-cell infiltration into the tumour microenvironment." (PMID 37211606, 2023). "In addition to enabling immune surveillance in the tumor microenvironment, STING agonists promote tumor regression by activating NLRP3 inflammasomes." (PMID 37036972, 2023).
tumor (continued). "Within the tumor, only 3 mononuclear phagocytes - CD16+ monocytes, NLRP3+ macrophages, and INHBA+ macrophages – had elevated levels of NLRP3 and IL1B expression." (PMID 36439171, 2022). "Petrilli and colleagues reported an immunosuppressive role of the Nlrp3-Asc-Caspase-1 pathway, that blunted NK cell tumor recruitment and activation, but that was independent of IL-1β, IL-18 or IL-1 receptor signaling." (PMID 35517498, 2022). "Of interest, the combination of the NLRP3 inhibitor with anti-CTLA-4/anti-PD-1 did not demonstrate a significant synergistic effect in regard to tumor growth but only in the frequencies of MDSC subsets." (PMID 36032139, 2022). "Notably, therapeutic inhibition of inflammasome significantly decreased tumor development and re-arranged the MDSC subsets, mirroring the effect described in Nlrp3-/- animals." (PMID 36032139, 2022). "Multiple inflammasomes, including NLRP3, NLRC4, NLRP1, and AIM2, may inhibit tumor initiation by influencing innate and adaptive immunity, apoptosis, and differentiation." (PMID 36437954, 2022). "We found that myeloid intrinsic NLRP3-mediated activation of caspase-1 and subsequent IL-1β release is permissive towards tumor growth, and that caspase-1 regulates the survival but not trafficking of the myeloid cells to the TME." (PMID 36439171, 2022). "Finally, pharmacologic inhibition of inflammasome, attenuates tumor growth and re-programs the MDSC compartment in a similar fashion to genetic silencing of Nlrp3." (PMID 36032139, 2022). "We found that NLRP1 had opposite expression differences in two GC datasets, whereas NLRP3 showed no differential expression between tumor and normal tissues." (PMID 36541912, 2022). "As the key trigger of pyroptosis, the NLRP3 inflammasome activated by dying tumor cells can stimulate DCs, thus effectively priming CD8+ T cells by secreting IL-1β, and thereby inducing a strong and durable tumor immune response." (PMID 36513682, 2022). "CASP8, CASP6, GSDME, NOD1, and GPX4 were significantly upregulated in tumor tissues compared to the normal tissues, whereas IL6, IL1B, NLRP3, and NLRC4 were downregulated, suggesting that pyroptosis-related genes play important roles in tumor progression and prognosis." (PMID 35559014, 2022). "In the subcutaneous tumour-bearing experiment involving NSG mice, due to the high expression of NLRP3 induced by Fn infection, a large number of MDSCs were enriched in the tumour and were no longer sensitive to CDDP treatment." (PMID 35435776, 2022). "To conclude, these data suggest that Nlrp3-/- mice did not exhibit differences in the hematopoietic progenitors but granulocyte progenitors are decreased in tumor-bearing animals." (PMID 36032139, 2022). "Likewise, most ICD-related genes, including IL-6, IL-10, NLRP3, CD8A, CD8B, and TLR4, exhibited attenuated expression levels in tumor cells compared to normal cells." (PMID 36225939, 2022). "Notably, we also showed that pharmacological inhibition of NLRP3 with the inhibitor OLT1177 reduces IL-1β levels, ultimately reducing tumor progression." (PMID 35631400, 2022). "Because the mechanisms through which NLRP1 and NLRP3 regulate tumor immune infiltration in GC are not clear, we performed GSEA, which revealed the potential biological pathways involving NLRP1/NLRP3." (PMID 36541912, 2022). "Our findings support the critical role of efferocytosis of tumor AC to activate NLRP3-dependent inflammasome signaling in the TME to induce non-pyroptotic IL-1β secretion which subsequently promotes tumor growth (Graphical Abstract)." (PMID 36439171, 2022).
tumor (continued). "In our previous study, we found that CuB at 100 nM could induce pyroptosis in A549 cells through TLR4/NLRP3/GSDMD signaling pathways, and administration with CuB at 0.25 mg/kg, 0.5 mg/kg and 0.75 mg/kg inhibited the tumor growth in NSCLC xenograft mice model." (PMID 35183200, 2022). "We selected C5AR1, CLEC4A and NLRP3 based on their significant protein expression in tumor-infiltrating lymphocytes, but not in normal lymphoid tissue." (PMID 36323738, 2022). "In the context of PANC, it has been demonstrated that the inhibition or deletion of components of the NLRP3 inflammasome, such as caspase-1, decreases tumor growth and metastasis in PANC by reprogramming innate and adaptive immunity in the tumor microenvironment." (PMID 35203699, 2022). "When released into tumor microenvironment, ATP acts on P2X7 purinergic receptors and triggers the NOD-like receptor family, pyrin domain containing-3 protein (NLRP3), allowing for the secretion of interleukin-1beta (IL-1β) then primes IFNγ-producing tumor antigen-specific CD8+ T cell in mice." (PMID 34094967, 2021). "NLRP3 signaling has been shown to promote tumor growth in PDAC; therefore, we hypothesized that the NLRP3-IL1β inflammasome may be activated in the orthotopic model and may contribute to the pro-tumoral immune response." (PMID 34198548, 2021). "Several studies have already illustrated the anti-inflammatory and anti-tumor effects of parthenolide(PTL) and its derivatives which inhibit the activity of Nuclear factor-κB (NF-κB), NLR family Pyrin domain containing 3 (NLRP3), and cysteine-aspartic acid protease 1(Caspase1)." (PMID 35096301, 2021). "The combination of NLRP3 inhibition by dapansutrile (OLT1177) and anti-PD-1 treatment significantly increased the antitumor efficacy by reducing MDSCs expansion and limiting MDSCs-mediated T-cell suppression and tumor progression." (PMID 35003065, 2021). "Interestingly, NLRP3 is required for the suppression of CRC metastatic growth in the liver, and its tumor-suppressive function is mediated by IL-18 production, which acts on NK cells." (PMID 34064909, 2021). "For instance, lack of NLRP3 in mice significantly attenuated tumor burden than control wild-type mice via an NK cell and IFN-γ-dependent manner." (PMID 33821998, 2021). "We observed different NLRP3 and PYCARD expressions in non-tumor vs tumor areas (p<0.0001)." (PMID 34540671, 2021). "In addition, the reconstitution of NLRP3 inflammasome through the E2/ERβ/MAPK estrogen pathway seems to reverse the malignant phenotype of HCC, reinforcing its tumor-suppressive effect." (PMID 35008212, 2021). "To determine whether DDP-induced pyroptosis suppresses tumor growth and metastasis via MEG3/NLRP3/caspase-1/GSDMD pathway in vivo, we established a xenograft model of nude mice bearing the MDA-MB-231 cells." (PMID 34326697, 2021). "In conclusion, HDSB11 could alleviate cell proliferation and colony formation and induce apoptosis in vitro and tumor growth in vivo, partly via NF-κB and MAPK signaling pathways to suppress NLRP3 expression." (PMID 34239588, 2021). "NLRP3 also showed significant up-regulation (p ≤ 0.05) in non-tumour cells but not in the tumour cell lines." (PMID 35082671, 2021). "Moreover, extracellular ATP released by tumor cells after chemotherapy can promote anti-tumor immunity via signaling through ATP-receptors P2RX7 on DCs, thereby activating the NLRP3 inflammasome, enhancing IL-1β secretion and boosting CD8+ T cell priming." (PMID 33013685, 2020). "Immunohistochemical analysis of tumor samples showed that the expressions of NLRP3 inflammasome and IL-1β were inhibited in MNS+CIK groups, furtherly indicating that MNS inhibits tumor growth through NLRP3 inflammasome inhibition." (PMID 32974137, 2020).